LMNB1 (lamin B1)
Description:
Lamins are intermediate filament proteins that assemble into a filamentous meshwork, and which constitute the major components of the nuclear lamina, a fibrous layer on the nucleoplasmic side of the inner nuclear membrane. Lamins provide a framework for the nuclear envelope, bridging the nuclear envelope and chromatin, thereby playing an important role in nuclear assembly, chromatin organization, nuclear membrane and telomere dynamics. The structural integrity of the lamina is strictly controlled by the cell cycle, as seen by the disintegration and formation of the nuclear envelope in prophase and telophase, respectively. Plays a role in sperm morphological development during late stages of spermiogenesis, particularly the anchoring of the sperm head to the tail. Component of the LMNB1/SUN5/SEPT12 bridge that connects the sperm proximal centriole to the implantation fossa, the bridge functions to prevent detachment of the proximal centriole from the posterior nucleus during spermiogenesis.
Synonyms: LMN2; LMNB; ADLD; LMN; MCPH26
Tractability: Small molecule: a structure with a bound ligand is known. PROTAC: UniProt records ubiquitination sites on it; ubiquitination databases record sites on it; its protein half-life has been measured.
Target class: Structural protein
Gene: Protein-coding gene on chromosome 5 (126,776,623 to 126,837,232, forward strand). Ensembl gene ENSG00000113368.
Subcellular location: Nucleus lamina
Subcellular location (Human Protein Atlas): Nuclear membrane
Pathways (Reactome):
Cell Cycle: Depolymerization of the Nuclear Lamina; Initiation of Nuclear Envelope (NE) Reformation; Nuclear Envelope Breakdown
Signal Transduction: RHOD GTPase cycle; RHOF GTPase cycle
Cellular responses to stimuli: Formation of Senescence-Associated Heterochromatin Foci (SAHF)
Disease: Deregulated CDK5 triggers multiple neurodegenerative pathways in Alzheimer's disease models
Immune System: Gene and protein expression by JAK-STAT signaling after Interleukin-12 stimulation
Programmed Cell Death: Breakdown of the nuclear lamina
Reproduction: Meiotic synapsis
Gene Ontology:
Molecular function: protein binding; structural constituent of cytoskeleton; structural constituent of nuclear lamina; double-stranded DNA binding; phospholipase binding; sequence-specific double-stranded DNA binding
Biological process: nuclear envelope organization; heterochromatin formation; nuclear migration; nuclear pore localization; protein localization to nuclear envelope; cytoskeleton organization
Cellular component: membrane; nuclear envelope; nuclear lamina; nuclear membrane; nucleus; nucleoplasm; lamin filament; nuclear inner membrane; nuclear matrix; nuclear periphery
Genetic constraint (gnomAD): Loss-of-function variants: 15 observed, 42.01 expected, observed/expected ratio (o/e) 0.36, 90% interval 0.24 to 0.55. The upper end of that interval is the gene's LOEUF score, 0.55, which puts it in group 2 of 6, group 1 being the genes least tolerant of losing a copy. Missense variants: 552 observed, 573.64 expected, observed/expected ratio (o/e) 0.96, 90% interval 0.9 to 1.03. Synonymous variants: 249 observed, 222.19 expected, observed/expected ratio (o/e) 1.12, 90% interval 1.01 to 1.25.
Gene-disease validity (ClinGen):
ClinGen rates the evidence that LMNB1 causes each of these diseases.
microcephaly 26, primary, autosomal dominant (autosomal dominant): Definitive.
Homologues: Orthologues: chimpanzee LMNB1 (99% identical), macaque LMNB1 (99% identical), dog LMNB1 (98% identical), pig LMNB1 (98% identical), rabbit LMNB1 (97% identical), rat Lmnb1 (96% identical), mouse Lmnb1 (96% identical), guinea pig LMNB1 (79% identical), tropical clawed frog lmnb1 (71% identical), zebrafish lmnb1 (70% identical). Paralogues in human: LMNB2 (60% identical), LMNA (54% identical), PRPH (21% identical), KRT6A (21% identical), KRT6B (21% identical), DES (21% identical), KRT5 (21% identical), KRT6C (20% identical), KRT76 (20% identical), VIM (20% identical), KRT8 (20% identical), KRT75 (20% identical), and 56 more.
Diseases named in the same sentence as LMNB1 in open-access papers:
LMNB1 is named in the same sentence as 157 diseases in open-access papers, as found by Europe PMC text mining. Sharing a sentence is not in itself a finding about the gene and the disease. The quoted sentences say what the papers report.
breast carcinoma (31 papers, 2013 to 2025). "Conversely, in lung and breast cancers, downmodulation of LMNB1 has been associated with increased aggressiveness." (PMID 39866838, 2025). "Using a composite TIS signature involving p21WAF1/Cip1+, H3K9me3+, and lamin B1 loss, ∼41% of breast cancer samples with an incomplete or partial response to neoadjuvant chemotherapy showed marker expression consistent with a senescence-like phenotype." (PMID 41280927, 2025). "Earlier studies tended to correlate lower LMNB1 expression in breast cancer patients with poorer clinical outcomes, while higher LMNB1 expression levels are associated with better outcomes." (PMID 38824174, 2024). "In contrast, VDAC1P1 appears to be associated with lamin B1 (LMNB1) transcription factor, which is known to be overexpressed in several cancers, such as lung adenocarcinoma, breast cancer and leukemia." (PMID 37344914, 2023). "In a similar work, we have looked into the expression of three senescence-associated proteins, namely, p21Cip1, Lamin B1, and H3K9Me3 in 37 breast cancer tissue samples exposed to NAC and developing partial or incomplete pathological response." (PMID 37741850, 2023). "Our data are further in accordance to previously published manuscripts as both molecules, the LBR and LMNB1, are mentioned in association with cellular senescence and ageing in different cancer types like PC, breast cancer, HCC and adenocarcinoma." (PMID 35883595, 2022). "A study of LMNB1 mRNA expression in breast cancer tissues found that lower LMNB1 transcript levels were associated with worse clinical outcome." (PMID 36005596, 2022). "Subsequently, we sought to assess any potential association of lamin B1 protein expression in relation to breast cancer molecular subtyping, TNM stage, lymphovascular invasion and lymph node involvement." (PMID 35328162, 2022). "We then created a LMNB1 (lamin B1 encoding gene)-knockout (KO) MDA-MB-231 breast cancer cell line using the clustered regularly interspaced short palindromic repeats/ CRISPR-associated (CRISPR/Cas) genome editing tool." (PMID 33155082, 2022). "In that, lamin B1 expression was only explored at the message level, as a previous study showed that lower lamin B1 mRNA expression in breast cancer is associated with worse clinical outcomes." (PMID 35328162, 2022). "Lamin dysregulation is linked to cancer biology, for example, the upregulation of LMNB1 in primary prostate cancer (PC) as well as in breast cancer is related to poor disease-free survival." (PMID 35883595, 2022). "Five additional loci were newly associated with both DA and breast cancer risk in the same direction, identifying LMNB1, MKX, PRKG1, MRPL17, and SMIM25 as candidate genes for both DA and breast cancer risk." (PMID 33037222, 2020). "Consequently, the characterization of senescence-associated biomarkers, including lamin B1, should facilitate the assessment of clinical senescence in breast cancer patients, allowing for the selection of more effective therapeutic approaches." (PMID 35328162, 2022). "Interestingly, in breast cancer, a low LMNB1 expression level was associated with a poor clinical outcome; this result was in contrast to that observed in other tumors with low LMNB1 expression level." (PMID 38824174, 2024). "Contrary to the literature, high levels of Lamin B1, instead of Lamin A/C, correlated with increased nuclear stiffness in the studied breast cancer cell lines." (PMID 39759848, 2025). "Recent evidence on tumor models shows that lamin B1 is essential for tethering LADs at the nuclear lamina in breast cancer cells." (PMID 39866838, 2025). "Knockout of Lamin B1 in human breast cancer cells leads to detachment of LADs from the nuclear periphery, accompanied by global redistribution and decompaction of chromatin." (PMID 38261271, 2024). "These distinct dynamics of lamin A/C and lamin B1 suggested that lamin B1 primarily protected the nuclear lamina integrity during a rapid nuclear deformation in MCF7 breast cancer cells." (PMID 37218524, 2023).
breast carcinoma (continued). "On the other hand, lamin B1 reduction and nuclear softening occur in cell culture-based models of lung and breast cancer, and knockout of lamin A/C or induction of heterochromatin decondensation are both sufficient to decrease nuclear stiffness." (PMID 36756194, 2023). "Next, we investigated how lamin B1 KO affects LADs in human breast cancer cells using lamin A chromatin immunoprecipitation (ChIP)." (PMID 33155082, 2022). "Subsequently, the downregulation of lamin B1 can potentially be used to identify the induction of TIS in breast cancer patients following exposure to treatment." (PMID 35328162, 2022). "In our study, we investigated the expression of p21CIP1, H3K9Me3, and Lamin B1 using immunohistochemistry (IHC) to evaluate TIS induction in breast cancer patients who received NAC and developed partial or poor response to therapy." (PMID 33948615, 2021). "In this work, the expression of three senescence-associated markers (p21CIP1, H3K9Me3 (histone H3 lysine 9 trimethylation), and Lamin B1) was investigated in breast cancer samples that developed partial or incomplete pathological response to NAC (n=37)." (PMID 33948615, 2021). "We used the MDA-231 and BT-549 as well as MCF-7 cells, another classis type of breast cancer cell line, for analysis of spontaneous MN formation by immunofluorescent staining of Lamin B1 and NAT10." (PMID 34123836, 2021). "Detecting TIS based on a three-marker signature involving the downregulation of lamin B1 and Ki-67, as well as the upregulation of p16INK4a revealed that 31% of breast cancer samples exhibited a shift toward a TIS-positive phenotype after exposure to neoadjuvant chemotherapy." (PMID 41280927, 2025). "Moreover, lamin B1 appears to be more reliable in reflecting a senescent state in breast cancer following exposure to NAC than other established senescence-associated markers such as p21Cip1 and H3K9Me3." (PMID 35328162, 2022). "In contrast, in human breast cancer cells in our study, disruption of lamins can lead to global chromatin decompaction, which is in accordance with decondensation of chromosomes 18 and 19 in lamin B1 RNAi DLD-1 cells." (PMID 33155082, 2022). "Besides, proteomic data from CPTAC also demonstrated that lamin B1 expression in the protein level was upregulated in breast cancer and lung adenocarcinoma." (PMID 35241075, 2022). "In this work, we aimed to characterize lamin B1 expression in breast cancer tissue and the change in protein expression levels that might occur in response to exposure to senescence-inducing chemotherapy." (PMID 35328162, 2022). "Overexpression of LMNB1 indicates lower survival rates both in pancreatic cancer and colon cancer, while upregulation of LMNB1 represents good clinical outcome in breast cancer." (PMID 31105744, 2019). "Decreased LMNB1 is a poor prognosis marker in breast cancer." (PMID 27449096, 2016). "By combining imaging and sequencing techniques, lamin B1 (and its interaction with the nuclear lamina) emerged as a critical element for maintaining LADs, compacting chromatin, organizing chromosome territories, and delineating A/B compartments in human breast cancer cells." (PMID 39866838, 2025). "Taken together, this evidence suggested that higher lamin B1 expression and larger nuclear lamina surface areas might limit cell death during extreme cell deformation which contributed to a mechanoresilient breast cancer subpopulation after mechanical selection." (PMID 37218524, 2023). "Some reports indicated that Lamin B1 expression is reduced in normal human fibroblast and mouse cell lines by various stimuli such as DNA damaging agents, replicative exhaustion, or oncogenic signaling; however, unfortunately, the evidence in clinical breast cancer samples is scarce." (PMID 33948615, 2021).
breast carcinoma (continued). "Previously, single-color dSTORM in FFPE human breast cancer tissue provided insight into the nanoscale organization of the cell membrane marker HER2, the outer mitochondrial membrane protein TOM20 and Lamin B1, a component of the nuclear envelope." (PMID 37484912, 2023). "Single-color SMLM in human FFPE breast cancer tissue allowed insights into the nanoscale organization of the cell membrane marker HER2, outer mitochondrial membrane protein TOM20 and Lamin B1, a component of the nuclear envelope." (PMID 37484912, 2023). "Prognostic analyses further revealed that LMNA, LMNB1, and LMNB2 expression all had prognostic value in the distant metastasis‐free survival (DMFS) of breast cancer patients." (PMID 37218524, 2023). "HER2+ breast cancer samples stained with CK19, Lamin B1 and HER2 Ab-oligo conjugates showed the expected staining patterns after incubation with their respective 28 nt complementary IS, each labeled with a spectrally distinct fluorophore." (PMID 34903759, 2021). "In this study, however, the study population excluded stage IV breast cancer patients, and LMNB1 expression showed no prognostic value; therefore, the findings need to be verified by more representative studies." (PMID 38824174, 2024). "Presently, the comparison of the expression level of LMNB1 in breast cancer tissues and normal breast epithelium has not received considerable attention." (PMID 38824174, 2024). "The effects of treatment with Sepin-1 that are similar on the four breast cancer cell lines include non-activation of caspases 3 and 7 and downregulation of cell cycle-driving proteins, such as Raf, FoxM1, Plk1, Cdk1, Aurora A, Lamin B1, and pericentrin." (PMID 29780443, 2018). "This set comprised senescence markers (CDKN1A, LMNB1, MKI67), apoptosis regulators (BCL2, BCL2L1), a highly overexpressed gene (ITGB6), and drug targets (ACTA2, GSDMC, KRT6A, PDE1A, PSMA8), all of which showed strong concordance with our RNA-seq data in all four breast cancer cell lines." (PMID 40312750, 2025). "Therefore, we concluded that there was no prognostic value of lamin B1 expression based on our analysis and the studied breast cancer samples." (PMID 35328162, 2022). "The status of lamin B1 protein expression in breast cancer has not been investigated." (PMID 35328162, 2022). "Alongside with the established senescence markers like CDKN1A and LMNB1, our transcriptome analysis identified a distinctive expression pattern, comprising genes upregulated across all cell lines exclusively during TIS, which may serve as a specific TIS signature in breast cancer." (PMID 40312750, 2025). "Moreover, the data indicate oligomerisation differences in SUN2 and Lamin B1, between non-invasive mammary epithelium (MCF10A) and invasive cancer (MDA-MB-231) cells in vitro, suggesting a mechanism by which the LINC complex influences breast cancer cell behaviour." (PMID 38891038, 2024).
laminopathies (22 papers, 2007 to 2025). "We compared the detailed clinical features of these LMNB1-deficient laminopathies with DS (from literature) and CRO1 child (this work) phenotypes." (PMID 37451904, 2023). "Collectively, the expression of progerin or prelamin A in fibroblasts derived from these three laminopathies-caused alterations in A-type lamin proportions and, in addition, in lamin B1." (PMID 37408186, 2023). "This opens up a theoretical possibility of early therapeutic interventions quenching the action of DYRK1A, in order to restore the levels of Lamin B1, and stop further development of laminopathy-associated phenotypes." (PMID 37451904, 2023). "Unlike the increased expression of lamin components reported in central or peripheral neuropathies caused by laminopathies, we detected and report for the first time, a lesser expression of Lamin B1 in SC of mutated TrJ concerning Wt genotype." (PMID 35327648, 2022). "The autosomal‐dominant leukodystrophy (ADLD, OMIM #169500) is the only laminopathy currently linked to the gene LMNB1, mainly caused by its duplication." (PMID 29696758, 2018). "Treatment of T-CRO1 organoids with DYRK1A inhibitors for 40 days significantly reduced the DSB and p21 values, and restored the Lamin B1 levels, demonstrating that this senescence and laminopathy-associated effect of DYRK1A can be, in principle, chemically counter-acted." (PMID 37451904, 2023). "Indeed, a growing range of human disorders have been linked to lamin B1 or B2, increasing the complexity of the group of diseases collectively known as laminopathies." (PMID 35132494, 2022). "Interestingly, autosomal dominant leukodystrophy, a laminopathy caused by the duplication of the LMNB1 gene, courses with severe central nervous system affectation, whose symptoms recall those of HD." (PMID 33369245, 2021). "Recently, however, several novel laminopathy cases with heterozygous null mutations in LMNB1, causing decreased Lamin B1 levels were described." (PMID 37451904, 2023). "Lamin B1 expression was significantly lower in all three laminopathies, with HGPS and MADB cells having the lowest expression levels." (PMID 37408186, 2023). "Disruption of lamin B1, major structural and functional member of the nuclear lamina, is observed in human laminopathies and in sporadic cancers, and leads to chromosomal rearrangements and alterations of gene expression." (PMID 36461070, 2022). "Our research identifies cathepsin L as a newly identified lamin B1 protease and mediator of laminopathy observed in AD." (PMID 34905652, 2022). "Because of the known abnormalities in the lamin A/C network in laminopathy patient dermal fibroblasts, we predicted that even in apparently normal-looking laminopathy cells, the lamin A/C and lamin B1 co-localization would be reduced compared to nHDF cells." (PMID 34638534, 2021). "In conclusion, our findings establish heterozygous variants in LMNB1 and LMNB2 as causes of primary microcephaly, implicating the nuclear lamina in its etiology and defining a novel form of laminopathy." (PMID 33033404, 2021). "Similar to lamin-A/C-related laminopathies, while LMNB1 and LMNB2 are also linked to disease, very few if any diseases have been linked to mutations in the LMNB1 and LMNB2 genes." (PMID 34455929, 2021). "In this regard, our study offers a new perspective on the less studied LMNB1 in the context of normal physiology and perhaps in laminopathies/disease." (PMID 30858340, 2019). "The lamin B1 layer thickness in the laminopathy patient fibroblasts appeared to be significantly larger in both confocal and STED images of separate and co-stained cells, while for lamin A/C only in confocal images of separately stained cells a significant difference was found." (PMID 34638534, 2021).